Y_RNA (Y RNA )
Gene: Miscellaneous RNA gene on chromosome 17 (62,122,320 to 62,122,421, forward strand). Ensembl gene ENSG00000207123.
Homologues: Orthologues: chimpanzee Y_RNA (96% identical), macaque Y_RNA (90% identical). Paralogues in human: Y_RNA (94% identical), RNY3 (93% identical), Y_RNA (93% identical), RNY3P1 (92% identical), Y_RNA (92% identical), Y_RNA (91% identical), Y_RNA (90% identical), Y_RNA (89% identical), RNY3P14 (88% identical), RNY3P5 (88% identical), Y_RNA (88% identical), RNY3P11 (87% identical), and 99 more.